DLGAP1-AS3 (DLGAP1 antisense RNA 3)
Gene: Long non-coding RNA gene on chromosome 18 (3,878,058 to 3,897,069, forward strand). Ensembl gene ENSG00000263724.
Gene Ontology:
Molecular function: U4 snRNA binding
Biological process: formation of quadruple SL/U4/U5/U6 snRNP; spliceosomal tri-snRNP complex assembly
Cellular component: U4/U6 x U5 tri-snRNP complex; U6 snRNP